MMP9 (matrix metallopeptidase 9)
Diseases named in the same sentence as MMP9 in open-access papers (continued):
Sharing a sentence is not in itself a finding about the gene and the disease.
hepatocellular carcinoma (continued). "We choose hepatocellular carcinoma cell line SMMC7721 for the establishment of in vitro invasion and metastasis model according to the expression levels of GRP78, MMP-2, MMP-9, MMP-14 and TIMP-2." (PMID 22546345, 2012). "In this study, our results showing the dependence of MMP-9 expression and invasive capacity of hepatoma cells on activity of AKT and ERK pathways can partly account for the high hepatoma cell aggressiveness." (PMID 21738655, 2011). "HBx can increase the migratory phenotype of hepatoma cells through the up-regulation of matrix metalloproteinases-1 (MMP1) and MMP9." (PMID 21078198, 2010). "Similarly, in hepatocellular carcinoma, caudatin-induced inhibition of Wnt/β-catenin signaling suppressed COX-2 (Cyclooxygenase-2) and MMP-2/MMP-9 expressions to favor inhibited metastasis (Row 2)." (PMID 40959450, 2025). "It was discovered that TCs facilitated hepatocellular carcinoma metastasis, and the activation of the Raf/ERK signaling pathway and the downregulation of mi942-3p played crucial roles in enhancing MMP9 expression and promoting hepatocellular carcinoma metastasis, respectively." (PMID 39605983, 2024). "Interestingly, in hepatocellular carcinoma (HCC) cells, higher matrix stiffness can enhance EMT and increase MMP-9 expression, suggesting a divergent role of MMP-9 from liver fibrosis to HCC progression." (PMID 38693104, 2024). "In a study by Zhao and co-workers on the hepatocellular carcinoma cell lines HepG2 and SK-Hep-1, Western blot analysis showed a significant reduction in MMP-2 and MMP-9 expression, resulting in strong anti-proliferative, anti-metastatic, and anti-invasive effects." (PMID 39335164, 2024). "Moreover, chlorogenic acid exhibited potent in vitro and in vivo antiproliferative activity against hepatocellular carcinoma by inducing cell cycle arrest in the S phase, reducing the phosphorylation of ERK1/2, and decreasing MMP-2 and MMP-9 expression." (PMID 39478959, 2024). "In addition, riboophorin II (RPN2) induces the expression of MMP-9 through the STAT3 and NF-kB pathways, thereby promoting hepatocellular carcinoma metastasis." (PMID 36950520, 2023). "Hence, our finding reveals that macrophage-derived MMP-9 and MMP-2 are closely related to the rupture of the FC of hepatocellular carcinoma leading to tumor invasion." (PMID 36918768, 2023). "However, in hepatocellular carcinoma studies, CXCL9 binds to the receptor subtype CXCR3 and activates the rhCXCL9-induced p-ERK1/2-MMP2/MMP9 pathway, enhancing the migration and invasion of CD133+ hepatocellular carcinoma." (PMID 36479091, 2022). "In addition, HDAC6 upregulation can inhibit the mesenchymal transformation of hepatocellular carcinoma (HCC) epithelial cells by increasing the level of E-cadherin protein and reducing the levels of N-cadherin, vimentin, and MMP-9 proteins." (PMID 35449808, 2022). "As we have shown in the previous sections, mortalin promoted the migration and invasion of hepatocellular carcinoma cells via RECK/STAT3 signaling, and Sal B inhibited EMT, the RECK/STAT3 pathway, MMP9/MMP2, and the migration and invasion of hepatocellular carcinoma cells." (PMID 34876128, 2021). "CTHRC1 promotes invasiveness and metastasis of hepatocellular carcinoma through the activation of PI3K/protein kinase B (PKB)/AKT/ERK/cAMP response element-binding protein (CREB) signaling pathway, which induces EMT change and MMP2/MMP9 expression." (PMID 32848510, 2020). "IFITM3 enhanced the invasion and metastasis of hepatocellular carcinoma through regulating expression of MMP9 via the p38/MAPK pathway and promoted proliferation of hepatocellular carcinoma via regulating expression of c-myc through the ERK1/2 signaling pathway." (PMID 33384961, 2020). "Hydroxysafflor yellow A could inhibit hepatocellular carcinoma through the inhibition of MMP-2, MMP-9, and p38MAPK signaling pathways in HepG2 cells." (PMID 32210799, 2020).
hepatocellular carcinoma (continued). "In hepatoma cells, expression of MT1-MMP, MMP-2, and MMP-9 facilitates stromal invasion." (PMID 30970564, 2019). "In the present study, we found that in liver cancer cells, including Hepa1-6 cells and HepG2 cells, sja-miR-7-5p inhibited the growth and migration of both mouse and human hepatoma cells by targeting SKP2 to elevate the expression of P27 and decrease the expression of MMP9." (PMID 30967999, 2019). "Baicalein, another antineoplastic compound of Chinese herbs, also inhibited the expression of MMP-9 and MMP-2 via reducing expression of protein kinase Cα (PKCα) and p38 mitogen-activated protein kinase (p38 MAPK) levels in poorly differentiated hepatoma cells." (PMID 27042656, 2016). "In conclusion, our study demonstrates that miR-324-5p suppresses hepatocellular carcinoma cell invasion by attenuate the expression and activity of MMP2 and MMP9, subsequently counteracting ECM degradation, through post-transcriptionally downregulating ETS1 and SP1." (PMID 26177288, 2015). "On the contrary, it has been shown that MMP-9 has a great value in the diagnosis of hepatocellular carcinoma; However, a study showed that MMP-9 levels were not significantly correlated to the fibrotic index of the liver in chronic HCV patients." (PMID 26464613, 2015). "So far, it is known that KLF4 acts as a tumor suppressor by positively regulating the levels of E-cadherin in hepatocellular carcinoma, MMP-2 and MMP-9 metalloproteases in neuroblastoma and the TF Slug during the epithelial to mesenchymal transition of mammary epithelial cells." (PMID 25181544, 2014). "Our in vivo results revealed that bufalin was able to decrease MMP-2 and MMP-9 expression levels in a dose-dependent manner, whereas our previous in vitro experiments show that bufalin is able to decrease MMP-2 and MMP-9 expressions in hepatoma cell lines." (PMID 24581171, 2014). "Likewise, miR-181b can enhance matrix metallopeptidases (MMP) 2 and MMP9 activity and promoted growth, clonogenic survival, migration and invasion of hepatocellular carcinoma (HCC) cells by modulating a tumor suppressor, the tissue inhibitor of metalloprotease 3 (TIM3)." (PMID 23533632, 2013). "Human hepatocellular carcinoma cell line SMMC7721 and HepG2 were cultured in DMEM supplemented with 10% FBS, RT-PCR and western blot were used to detect the endogenous expression of GRP78, MMP-2, MMP-9 and TIMP-2 in SMMC7721 and HepG2." (PMID 22546345, 2012). "Abnormal expression of MMPs is believed to play an important role in tumor cell invasion and metastasis in human cancers, including hepatocellular carcinoma.Among the MMPs, the roles of MMP-2 and MMP-9 in the invasiveness and metastasis of cancer cells are well characterized." (PMID 22546345, 2012). "A recent study found that silencing β-catenin expression by RNA interference could inhibit angiogenesis-related gene expression (e.g., MMP9, MMP2, and VEGF) in hepatocellular carcinoma cells." (PMID 22957092, 2012). "In an animal model, the administration of black-tea polyphenon-B significantly reduces the incidence of dimethylaminoazobenzene (DAB)-induced hepatomas as evidenced by modulation of RECK, matrix metalloproteinase (MMP)-2, MMP-9, and the tissue inhibitor of matrix metalloproteinase-2." (PMID 22428065, 2012). "In conclusion, our results suggest that berberine may be a potential alternative against invasive hepatoma cells through PI3K-AKT and ERK pathways-dependent downregulation of MMP-9 expression." (PMID 21738655, 2011). "Moreover, the expression of MMP9 was predominantly observed in monocytes rather than hepatoma cells." (PMID 38254761, 2024). "HuR targets include invasive and metastatic RNAs (e.g., MMP-9, MTA1, and uPA), angiogenic RNAs (e.g., VEGF-1 and HIF-1), and cell proliferative RNAs (e.g., EGF, cyclin A, cyclin B1, cyclin E, and cyclin D1), through which it can influence hepatocellular carcinoma progression." (PMID 37540723, 2023).
hepatocellular carcinoma (continued). "Serum MMP-9 and MMP-2 cutoff values can effectively predict whether FC is ruptured in patients with hepatocellular carcinoma pre-operatively, determine the range of surgery, and provide a new diagnostic method for clinical therapy, which is of guiding significance." (PMID 36918768, 2023). "Additionally, this research found that MMP-9/MMP-2 ratios in advanced, inoperable hepatitis B virus-related hepatocellular carcinoma patients were significantly higher than those in early-stage hepatitis B virus-related hepatocellular carcinoma patients." (PMID 30262739, 2018). "Pterostilbene inhibited tumor in human hepatocellular carcinoma cells by suppressing various signal transduction pathways, including mitogen-activated protein kinase (MAPK), NF-κB, matrix metalloproteinase-9 (MMP-9), expression of vascular endothelial growth factor (VEGF) and AP-1." (PMID 29109374, 2017). "Studies in hepatocellular carcinoma and glioblastoma cell lines have shown that the activation of the PI3K/Akt pathway and subsequent NF-kB or mTOR activation upon radiation leads to the secretion of matrix metalloproteinases (MMP), mainly MMP-2 and MMP-9, and consequently to enhanced cell invasion." (PMID 27835571, 2016). "For example, mTOR signaling may be activated by the upregulation of MMP-9 but not by that of MMP-2 in hepatocellular carcinoma." (PMID 26202311, 2015). "Taken together, these results demonstrated that sinulariolide could inhibit hepatocellular carcinoma cell migration and invasion and alter HA22T cell metastasis by reduction of MMP-2, MMP-9, and uPA expression through the suppression of MAPKs, PI3K/Akt, and the FAK/GRB2 signaling pathway." (PMID 26204832, 2015). "RhoGDI2 has been shown to be upregulated in hepatocellular carcinoma (HCC) cells where its overexpression increased their rates of proliferation and invasion, via activating the PI3K/Akt pathway and increasing the levels of MMP2 and MMP9 (consistent to PDAC)." (PMID 36835422, 2023). "In conclusion, MMP-9 and MMP-2 were able to effectively differentiate between ruptured FC and intact FC, both on the tissue level and on the serum level, suggesting that it has great potential in diagnosing whether FC is ruptured in patients with hepatocellular carcinoma." (PMID 36918768, 2023). "Furthermore, recent findings demonstrate that NRF2 expression is upregulated in human hepatocellular carcinoma (HCC) and that NRF2 promotes proliferation and tumor metastasis by regulating Bcl-xL and MMP-9 genes expression." (PMID 32106613, 2020). "In addition, the migratory effect of fascin-1 on hepatocellular carcinoma cells led to efficient invasion when assisted with secretory factors from intrinsically highly invasive cells such as MMP-9, which fascin-1 alone could not up regulate." (PMID 24993803, 2014). "We found in CRC that although MMP-9 levels had no influence on survival, patients with a low MMP-9/TIMP-1 ratio had impaired survival, in line with their results in hepatocellular carcinoma." (PMID 29929486, 2018). "In hepatocellular carcinoma cells, Grp78 knockdown inhibited ECM degradation and the decreased activity and expression of MMP-2, but not MMP-9 contributed largely to this impact." (PMID 22546345, 2012). "In addition to that, five miRNAs (miR-124-3p, miR-34a-5p, miR-1-3p, miR-7-5p, and miR-99b-5p) were found in human cells that might target four hub genes (CXCL2, MMP9, SPP1, and SRC), which are related to inflammatory bowel disease (IBD) and hepatocellular carcinoma (HCC)." (PMID 37298833, 2023). "Similarly, in hepatocellular carcinoma (HCC), miR-21 derived from the tumor reduces PTEN levels, leading to the activation of the PDK1/AKT signaling pathway and an increase in the expression of VEGF, MMP2, MMP9, βFGF, and TGF-β in CAFs, thereby promoting angiogenesis." (PMID 37605155, 2023). "However, no previous study has investigated the correlation between MMP-9 and MMP-2 and FC rupture in hepatocellular carcinoma." (PMID 36918768, 2023).
hepatocellular carcinoma (continued). "In addition, one study of four genes [E‐cadherin, MMP9 (matrix metalloproteinase‐9), TCF3 (transcription factor 3)/E47 and ID2 (inhibitor of differentiation 2)] has validated their prognostic value, in terms of overall survival, in a large cohort of hepatocellular carcinomas (HCC)." (PMID 28590039, 2017). "Further they noticed that there was positive correlation between lipocalin 2 (LCN2) and MMP-9 and negative correlation with tissue inhibitors of MMP (TIMPs) in the 3 studied groups suggesting that this may have role in progression of cirrhosis and hepatocellular carcinoma." (PMID 32856853, 2020). "The mRNA levels of both MMP-2 and MMP-14 in human hepatocellular carcinoma (HCC) cell SMMC-7721 were up-regulated by Cu2+ in a concentration dependent manner, whereas the mRNA levels for other tested MMPs (MMP-1, MMP-3 and MMP-9) were not changed when treated with up to 40 μM Cu2+." (PMID 28881637, 2017).
colorectal cancer (291 papers, 1995 to 2025). A primary or metastatic malignant neoplasm that affects the colon or rectum. "sLZIP binds to cAMP response elements (CREs) to activate MMP-9 transcription in cervical cancer and microtubule-associated protein 1A/1B-light chain 3 transcription in colorectal cancer." (PMID 39594816, 2024). "In the context of colorectal cancer, MMP9 has been associated with tumor growth and metastasis, while in neuropathic conditions like CIPN, it is implicated in neuronal damage." (PMID 39664453, 2024). "This desmoplastic stroma is common in more than 50% of colorectal cancers, suggesting that MMP9’s activity in stromal remodeling is associated with a more aggressive tumor phenotype." (PMID 39664453, 2024). "A deeper understanding of MMP9’s role in the pathogenesis of colorectal cancer and its associated neuropathic conditions is essential to anticipate patient outcomes and develop novel therapeutic approaches." (PMID 39664453, 2024). "Macrophages are integral to MMP9-associated pathways in both colorectal cancer and neuropathic pain." (PMID 39664453, 2024). "NF-κB was implied to contribute to metastasis and chemoresistance in colorectal cancer via MMP-9 upregulation, causing resistance to 5-FU." (PMID 35586209, 2022). "Compared to early stages of colorectal cancer, overexpression of MMP9 is strongly associated with more advanced stages." (PMID 36158686, 2022). "Increased expression of MMP-2 and MMP-9 in normal tumor-free mucosa adjacent to colorectal tumors was independently associated with poor prognosis in colorectal cancer patients." (PMID 34502094, 2021). "Mmp‐9 expression after metallic stent placement in patients with colorectal cancer: association with in‐stent restenosis." (PMID 33305454, 2021). "MMP-2 and MMP-9 were increased in the serum of colorectal cancer patients, and their diagnostic sensitivity was higher than that of other biomarkers currently used in clinical practice, such as CEA and CA19-9." (PMID 34502094, 2021). "Consistently, low level of SMAD4 has been found to associate with high MMP-9, resulting colorectal cancer malignance." (PMID 34743754, 2021). "The association of collagen IV, laminin, and matrix metallopeptidase 9 expression was demonstrated in colorectal cancer cells, in which there was an abnormal accumulation of laminin in the cytoplasm with an absence of basal membranes containing collagen IV." (PMID 34572445, 2021). "MMP-9 is a zinc ion proteolytic enzyme that can trigger a variety of inflammations, suggesting that the mechanism that MMP-9 involves in colorectal cancer is also associated with inflammation." (PMID 32461933, 2020). "Accumulating loss of SMAD4 leads to up-regulation of CCL15 and CCR1 expression, followed by higher activity and expression of MMP-9, ultimately causing colorectal cancer malignance." (PMID 30979374, 2019). "The aim of this study was to evaluate interleukin-6 (IL-6), C-reactive protein (CRP), matrix metalloproteinase-9 (MMP-9), serum levels in patients with colorectal cancer (CRC), and their association with the stage of CRC." (PMID 30154846, 2018). "Gelatinase B/MMP-9 has been reported to protect colorectal cancer cells against microsatellite instability, with reduced gelatinase B/MMP-9 activity associated with increased microsatellite instability." (PMID 24473089, 2014). "The gelatinases MMP-2 and MMP-9 are implicated in the process of colorectal cancer progression, angiogenesis and metastasis." (PMID 22472880, 2012). "In NSCLC and colorectal cancer, overexpressed MMP9 was markedly associated with shortened cancer-related survival." (PMID 20534121, 2010). "Our pilot suggests that MMP9 has potential in detecting those at risk of having colorectal cancer as it demonstrates a high specificity and positive predictive value." (PMID 19175925, 2009).